POLI (DNA polymerase iota)
Description:
Error-prone DNA polymerase specifically involved in DNA repair. Plays an important role in translesion synthesis, where the normal high-fidelity DNA polymerases cannot proceed and DNA synthesis stalls. Favors Hoogsteen base-pairing in the active site. Inserts the correct base with high-fidelity opposite an adenosine template. Exhibits low fidelity and efficiency opposite a thymidine template, where it will preferentially insert guanosine. May play a role in hypermutation of immunoglobulin genes. Forms a Schiff base with 5'-deoxyribose phosphate at abasic sites, but may not have lyase activity.
Synonyms: RAD30B; RAD3OB; eta2
Tractability: Small molecule: a structure with a bound ligand is known; a high-quality ligand is known; it has a binding pocket of medium quality. PROTAC: UniProt records ubiquitination sites on it; ubiquitination databases record sites on it; a small molecule that binds it is known.
Target class: Enzyme; Transferase
Gene: Protein-coding gene on chromosome 18 (54,269,510 to 54,321,266, forward strand). Ensembl gene ENSG00000101751.
Subcellular location: Nucleus
Subcellular location (Human Protein Atlas): Nuclear speckles; Cytoplasmic bodies
Pathways (Reactome):
DNA Repair: Termination of translesion DNA synthesis; Translesion synthesis by POLI
Gene Ontology:
Molecular function: DNA polymerase activity; DNA-directed DNA polymerase activity; protein binding; damaged DNA binding
Biological process: translesion synthesis; DNA repair; error-prone translesion synthesis
Cellular component: nuclear speck; nucleus; nucleoplasm
Genetic constraint (gnomAD): Loss-of-function variants: 11 observed, 10.23 expected, observed/expected ratio (o/e) 1.08, 90% interval 0.67 to 1.72. The upper end of that interval is the gene's LOEUF score, 1.72, which puts it in group 6 of 6, group 1 being the genes least tolerant of losing a copy. Missense variants: 462 observed, 413.17 expected, observed/expected ratio (o/e) 1.12, 90% interval 1.03 to 1.21. Synonymous variants: 165 observed, 150.83 expected, observed/expected ratio (o/e) 1.09, 90% interval 0.96 to 1.25.
Homologues: Orthologues: chimpanzee POLI (99% identical), macaque POLI (95% identical), pig POLI (83% identical), dog POLI (80% identical), rat Poli (79% identical), mouse Poli (76% identical), guinea pig POLI (69% identical), tropical clawed frog poli (43% identical), zebrafish poli (39% identical), Drosophila melanogaster PolI (28% identical). Paralogues in human: POLH (21% identical), POLK (19% identical), REV1 (19% identical), ESCO1 (8% identical), ESCO2 (8% identical).
Diseases named in the same sentence as POLI in open-access papers:
POLI is named in the same sentence as 31 diseases in open-access papers, as found by Europe PMC text mining. Sharing a sentence is not in itself a finding about the gene and the disease. The quoted sentences say what the papers report.
esophageal squamous cell carcinoma (4 papers, 2021 to 2024). Esophageal squamous cell carcinoma (ESCC) is a type of esophageal carcinoma (EC) that can affect any part of the esophagus, but is usually located in the upper or middle third. "Similarly, upregulation of POLI predicted poor prognosis in esophageal squamous cell carcinoma (ESCC) patients." (PMID 36497462, 2022).
lung adenocarcinoma (3 papers, 2020 to 2023). A carcinoma that arises from the lung and is characterized by the presence of malignant glandular epithelial cells. "Furthermore, the single amino acid polymorphism Thr706Ala in POLI was indicative of a higher risk of developing lung adenocarcinoma and squamous cell carcinoma in individuals of <61 years." (PMID 36497462, 2022). "Of the 144 LTL genetic instruments, 12 colocalised with lung adenocarcinoma risk and revealed novel susceptibility loci, including MPHOSPH6, PRPF6, and POLI." (PMID 37079368, 2023).
prostate carcinoma (3 papers, 2018 to 2026). A carcinoma that arises from epithelial cells of the prostate gland. "Summary-data-based Mendelian Randomization analysis identified significant associations of genetically predicted RPA2 and POLI with prostate cancer risk." (PMID 42216412, 2026). "Our study reveals a genetically inferred causal role for DDR-related genes RPA2 and POLI in prostate cancer risk." (PMID 42216412, 2026). "Immunohistochemical analyses from the human protein atlas database confirmed RPA2 and POLI expression in prostate cancer tissue, while single-cell sequencing data from the tumor immune single-cell hub 2 database indicated differential expression across distinct cellular subpopulations." (PMID 42216412, 2026).
influenza (2 papers, 2019 to 2022). An acute viral infection of the respiratory tract, occurring in isolated cases, in epidemics, or in pandemics; it is caused by serologically different strains of viruses (influenzaviruses) designated A, B, and C, has a 3-day incubation period, and usually lasts for 3 to 10 days. "The luciferase-based feline PolI influenza reporter construct was established, and it drove transcription immediately downstream of the predicted transcription initiation site of the feline RNA PolI promoter and expressed the corresponding reporter proteins." (PMID 35693765, 2022). "Primers were designed by extending homologous sequences containing Uni 12 or Uni 13 and conserved viral gene-specific sequences of the 8 influenza segments between the polI terminator and polI promotor sequences of the pHW2000 vector." (PMID 31165766, 2019).
lung carcinoma (2 papers, 2019 to 2023). "Several colocalised loci mapped to genes that have not been previously linked to lung cancer risk at genome-wide significant level: MPHOSPH6 (16q23.3; rs2303262), PRPF6 (20q13.33; rs80150989), and POLI (18q21.2; rs2276182)." (PMID 37079368, 2023).
lymphoma (2 papers, 2016 to 2023). A malignant (clonal) proliferation of B- lymphocytes or T- lymphocytes which involves the lymph nodes, bone marrow and/or extranodal sites. "We also found hotspot-enriched signatures related to UV (signatures 7a, 67, 75, 7b), POLE (62, 10a), POLI, lymphoma-linked, and several signatures of unknown etiologies (17b, 17a, 19, 68, 28, 30)." (PMID 37592287, 2023).
melanoma (2 papers, 2019 to 2022). A malignant, usually aggressive tumor composed of atypical, neoplastic melanocytes. "The classifier was then used to cluster patients with bladder, breast, colorectal, head and neck, liver, lung, ovary, melanoma, stomach, and uterus cancer when high POLI expression was associated with worsened survival (Group I) or with improved survival (Group II)." (PMID 35955705, 2022).
cardiac hypertrophy (1 paper, 2021). "Accelerated polymerase I (PolI) transcription rate increases ribosome numbers during the development of cardiac hypertrophy." (PMID 34977198, 2021). "Upstream binding transcription factor (UBTF) has been shown to regulate PolI transcription activity in cardiac hypertrophy." (PMID 34977198, 2021). "Accelerated PolI transcription activity increases ribosome numbers during the development of cardiac hypertrophy." (PMID 34977198, 2021).
cervical cancer (1 paper, 2022). A primary or metastatic malignant neoplasm involving the cervix. "To determine if the same was true for TLS genes other than the TLS polymerases (POLH, POLI, POLK, REV1, and REV3L), we segregated the cervical cancers in the TCGA database based on whether they did or did not have increased expression of at least one TLS gene." (PMID 36266721, 2022).
Fanconi anemia (1 paper, 2022). Fanconi anemia (FA) is a hereditary DNA repair disorder characterized by progressive pancytopenia with bone marrow failure, variable congenital malformations and predisposition to develop hematological or solid tumors. "Hsa_circ_0003428 was formed from POLI, which was enriched in the “Fanconi anemia pathway”." (PMID 36077296, 2022).
pancreatic cancer (1 paper, 2022). "Building upon current knowledge, we found that the expression of one of these TLS polymerases (POLI) is associated with significant differences in cervical and pancreatic cancer survival." (PMID 35955705, 2022). "We presented a binary cancer random forest classifier using 396 genes that influence the prognostic characteristics of POLI in cervical and pancreatic cancer selected via graphical least absolute shrinkage and selection operator." (PMID 35955705, 2022).
Treacher-Collins syndrome (1 paper, 2015). A congenital disorder of craniofacial development characterized by bilateral symmetrical oto-mandibular dysplasia without abnormalities of the extremities, and associated with several head and neck defects. "Treacher Collins syndrome (TCS) is caused by mutations in genes involved in rRNA transcription, such as the Treacher Collins-Franceschetti syndrome 1 (TCOF1) and POLR1D and POLR1C genes, which encode subunits of RNA polymerase I and III (PolI/III)." (PMID 26398160, 2015).
cancer (22 papers, 2009 to 2023). A tumor composed of atypical neoplastic, often pleomorphic cells that invade other tissues. "ISP I, however, modulates POLI transcriptional function by inducing nucleolar endogenous oxidative stress, to which cancer cells are susceptible." (PMID 35387667, 2022). "The accumulation of ROS in the nucleolus triggers nucleolar stress and blocks ribosomal RNA transcription via the JNK2/TIF-IA/POLI pathway, causing cell cycle arrest and apoptosis in cancer cells." (PMID 35387667, 2022). "Together with the work of others, our results suggest that POLI gene may be a cancer susceptibility gene being special DNA damage induced mutation spectrum." (PMID 23922701, 2013). "Metarrestin, which disrupts nucleolar structure and restricts POLI transcription, suppresses metastasis in mouse models of human cancer." (PMID 35387667, 2022). "This was our rationale for using the expression data of genes correlating with POLI expression as the input for a cancer classifier." (PMID 35955705, 2022). "The backward selection was performed to select cancer types that the prognosis of POLI expression would stand out from Group 1 and Group 2, respectively." (PMID 35955705, 2022). "This approach allowed us to identify cancers where POLI expression is a significant prognostic factor for survival (p = 0.028 in Group I and p = 0.0059 in Group II)." (PMID 35955705, 2022). "New inhibitor of POLI (RNA polymerase) CX‐5461 was described to have preferential activity against cancer cells and its efficacy increased in taxane‐resistant OC cells." (PMID 30499260, 2019). "Thanks to the extensive understanding about the molecular mechanisms (mis)regulating rRNA transcription in cancer, compounds targeting the PolI transcriptional machinery are currently in clinical trials to treat different types of cancer." (PMID 31533350, 2019). "Two recently described drugs, CX-5461 and BMH-21, are reported to inhibit PolI activity more specifically, with promising therapeutic potential in the treatment of cancer." (PMID 30556094, 2019). "Targeting the PolI molecular machinery represents the most established mechanism exploited by cancer cells to fuel the ribosomal biosynthesis process." (PMID 31533350, 2019). "In this manuscript, we probe transcriptomic data from the cancer genome atlas (TCGA) to identify genes associated with POLI expression being a positive/negative prognostic factor." (PMID 35955705, 2022). "Increased ribosome activity in cancer might form an Achilles’ heel, permitting selective targeting of tumor cells by PolI inhibitors." (PMID 30556094, 2019). "For new testing patients with other cancer types, RFC calculated the similarity between Group 1, “CESC-like” containing potential signal of increase in POLI expression worsening survival, and Group 2, “PAAD-like” containing potential signal of increase POLI expression improving survival." (PMID 35955705, 2022). "Given that PolI silencing induces NF-κB (RelA) displacement to the nucleolus, the PolI inhibitor BMH-21 may be used to sensitize cancer cells to apoptosis." (PMID 35620053, 2022). "Further, the classification scheme described here was not able to segregate several types of cancers based on their ability to predict this prognostic value of POLI expression." (PMID 35955705, 2022). "However, when cancers were grouped cancer type, POLI expression did not have a significant prognostic value." (PMID 35955705, 2022).
cancer (continued). "In a recent study with human HeLa cancer cells, 27 CpG sites in the upstream control element and core promoter of rRNA were in general highly methylated, but in DNA immunoprecipitated with antibody to PolI these sites had reduced or absent methylation." (PMID 19838300, 2009). "The authors go on to demonstrate that canonical ALT cells, likely due to their lack of functional ATRX, are equally sensitive to PolI inhibitors, suggesting that PolI inhibitors could be effective on a wide range of ALT cancers." (PMID 32039009, 2019). "Similarly, the small molecule PolI inhibitor, BMH-21, that is also showing promise as an anti-cancer agent, did not stimulate the NF-κB pathway." (PMID 30301139, 2018).
tumor (11 papers, 2013 to 2026). "Xenograft tumor growth was found to be dramatically delayed for POLI-deficient cells, but promoted for POLI-overexpressed cells compared to the control group after being exposed to the same IR treatment." (PMID 37558683, 2023). "Specifically, POLI mutations were found in only 3.0% of these tumors overall and there were only small variations in POLI mutation frequency among the tumor types analyzed in this study (1.4–5.0%)." (PMID 35955705, 2022). "To determine the likelihood that the results reported here were driven by POLI mutations among tumor types, we determined the frequency of POLI mutations in each TCGA database used for this analysis." (PMID 35955705, 2022). "Based on clinical sample analysis, it has been shown that POLI expression in tumor tissues is closely related to lymph node metastasis in ESCC tumors." (PMID 37558683, 2023). "Increased expression of POLI positively correlates with the degree of malignancy in tumour samples from BC patients." (PMID 36293346, 2022). "POLI was a significant prognostic factor in both of these tumor types." (PMID 35955705, 2022). "This supports our hypothesis that the prognostic value of POLI expression is determined by the transcriptome of an individual tumor." (PMID 35955705, 2022). "POLI, the only gene with a higher expression in XP-V tumor cells, may compensate for TLS." (PMID 24260050, 2013). "When compared the top 20% of VEGFA expressing tumor samples to the bottom 20% expressing tumors and found that POLH goes up 1.69-fold (FDR 1 × 10−10), POLI goes up 2.06-fold (FDR 1.3 × 10−15) and REV3L goes up 1.62-fold (FDR 3.8 × 10−6)." (PMID 39468223, 2025). "We observed that POLI expression did not correlate with survival in these tumor types when combined." (PMID 35955705, 2022). "qPCR results revealed that the mRNA quantities of POLH, POLK, POLQ and REV3L in XP-V tumor cells were lower than those of the controls; however, the expression of POLI was higher in the XP-V tumor cells in the absence of UV irradiation (P<0.05)." (PMID 24260050, 2013).
infection (4 papers, 2011 to 2017). The state of being infected such as from the introduction of a foreign agent such as serum, vaccine, antigenic substance or organism. "In contrast, genes in a cluster known to regulate nucleoplasm architecture such as HDAC11, CCNE2, and POLI reduced infection upon depletion." (PMID 24874089, 2014). "While initial transcription events in this system require PolI driven plasmid transcription, for most of the 48 h time course of the assay virus proteins are synthesised from the newly synthesised virus RNAs as they are in a natural infection." (PMID 28738877, 2017). "FluA polI-Gluc-transfected A549 cells were infected with influenza virus G1 (MOI of 1), and supernatants were harvested for luciferase analysis at 0, 3, 6, 9, 12, and 24 h post-infection (p.i.)." (PMID 21251302, 2011).
POLI also shares sentences with these, for which no sentence is quoted: asthma (2 papers); depression (2); adult onset asthma (1); allergic disease (1); Anxiety (1); Bladder Cancer (1); breast carcinoma (1); colorectal tumours (1); endometrial cancer (1); esophagus tumors (1); genetic disorders (1); Onset (1); squamous cell carcinoma (1); Thyroid Carcinoma (1); uterine corpus endometrial carcinoma (1); uterus cancer (1).